MIR4266 (microRNA 4266)
Synonyms: hsa-mir-4266
Gene: MicroRNA gene on chromosome 2 (109,313,571 to 109,313,625, reverse strand). Ensembl gene ENSG00000265965.
Diseases named in the same sentence as MIR4266 in open-access papers:
MIR4266 is named in the same sentence as 1 disease in open-access papers, as found by Europe PMC text mining. Sharing a sentence is not in itself a finding about the gene and the disease.
MIR4266 shares sentences with these, for which no sentence is quoted: infection (1 paper).